ATP6V0B (ATPase H+ transporting V0 subunit b)
Description:
Proton-conducting pore forming subunit of the V0 complex of vacuolar(H+)-ATPase (V-ATPase), a multisubunit enzyme composed of a peripheral complex (V1) that hydrolyzes ATP and a membrane integral complex (V0) that translocates protons. V-ATPase is responsible for acidifying and maintaining the pH of intracellular compartments and in some cell types, is targeted to the plasma membrane, where it promotes acidification of the extracellular environment (By similarity). The V-ATPase complex also acts as an activator for mTORC1 on lysosomal membrane by promoting the guanine nucleotide exchange factor (GEF) of the Ragulator complex, thereby enabling mTORC1 recruitment.
Synonyms: ATP6F; VMA16; HATPL
Tractability: Small molecule: a structure with a bound ligand is known. Antibody: UniProt predicts a signal peptide or a membrane-spanning region.
Gene: Protein-coding gene on chromosome 1 (43,974,487 to 43,978,295, forward strand). Ensembl gene ENSG00000117410.
Subcellular location: Cytoplasmic vesicle, clathrin-coated vesicle membrane
Subcellular location (Human Protein Atlas): Cytosol
Pathways (Reactome):
Transport of small molecules: Ion channel transport; Transferrin endocytosis and recycling
Cellular responses to stimuli: Amino acids regulate mTORC1
Developmental Biology: Regulation of MITF-M-dependent genes involved in lysosome biogenesis and autophagy
Immune System: ROS and RNS production in phagocytes
Signal Transduction: Insulin receptor recycling
Gene Ontology:
Molecular function: protein binding; proton-transporting ATPase activity, rotational mechanism; proton transmembrane transporter activity
Biological process: endosomal lumen acidification; Golgi lumen acidification; intracellular pH reduction; lysosomal lumen acidification; proton transmembrane transport; regulation of macroautophagy; vacuolar acidification
Cellular component: membrane; endosome membrane; Golgi membrane; lysosomal membrane; phagocytic vesicle membrane; plasma membrane; proton-transporting V-type ATPase complex; vacuolar proton-transporting V-type ATPase, V0 domain; clathrin-coated vesicle membrane; endosome; proton-transporting two-sector ATPase complex, proton-transporting domain; proton-transporting V-type ATPase, V0 domain
Genetic constraint (gnomAD): Loss-of-function variants: 4 observed, 24.62 expected, observed/expected ratio (o/e) 0.16, 90% interval 0.079 to 0.37. The upper end of that interval is the gene's LOEUF score, 0.37, which puts it in group 1 of 6, group 1 being the genes least tolerant of losing a copy. Missense variants: 175 observed, 267.03 expected, observed/expected ratio (o/e) 0.66, 90% interval 0.58 to 0.74. Synonymous variants: 110 observed, 103.51 expected, observed/expected ratio (o/e) 1.06, 90% interval 0.91 to 1.25.
Homologues: Orthologues: rabbit ATP6V0B (99% identical), guinea pig ATP6V0B (98% identical), pig ATP6V0B (98% identical), dog ATP6V0B (98% identical), chimpanzee ATP6V0B (97% identical), mouse Atp6v0b (96% identical), zebrafish atp6v0b (86% identical), tropical clawed frog atp6v0b (81% identical), Drosophila melanogaster VhaPPA1-1 (62% identical), Caenorhabditis elegans vha-4 (60% identical), Drosophila melanogaster VhaPPA1-2 (52% identical). Paralogues in human: ATP6V0C (25% identical).
Diseases named in the same sentence as ATP6V0B in open-access papers:
ATP6V0B is named in the same sentence as 16 diseases in open-access papers, as found by Europe PMC text mining. Sharing a sentence is not in itself a finding about the gene and the disease. The quoted sentences say what the papers report.
tuberculosis (2 papers, 2022 to 2023). A chronic, recurrent infection caused by the bacterium Mycobacterium tuberculosis. "ATPase H+ transporters, including ATP6AP1, ATP6V0B, and ATP6V0D1, were identified in the other module-related pathways such as lysosome, tuberculosis, and phagosome." (PMID 36034872, 2022).
Alzheimer disease (1 paper, 2021). A progressive, neurodegenerative disease characterized by loss of function and death of nerve cells in several areas of the brain leading to loss of cognitive function such as memory and language. "Ten DEGs, including IGF1, VEGFC, RAPGEF3, PIK3CA, Akt3, ITGB3, ITGA11, SPP1, NOS1, and ATP6V0B, were selected from Rap1, oxidative phosphorylation, and Alzheimer’s disease signaling pathways." (PMID 34359260, 2021).
cystic fibrosis (1 paper, 2020). Autosomal recessive disorder caused by pathogenic variants in the CFTR gene (cystic fibrosis transmembrane conductance regulator), which encodes a chloride and bicarbonate channel expressed in epithelial cells, and follow the diagnosis criteria. "Like ionocytes in mouse airways and human LAE, the human SAE ionocytes highly expressed the transcription factors FOXI1 and ASCL3, V-ATPase-subunit genes (ATP6V1G3, ATP6V0B), and the Cl− ion channel CFTR, that when mutated, causes cystic fibrosis." (PMID 32727470, 2020).
dysferlinopathy (1 paper, 2023). "Analysis of muscle transcripts from patients with dysferlinopathy helped identify the following 7 upregulated DEGs involved in the cellular response to stress: HSPA9, RPTOR, MTOR, LAMTOR1, LAMTOR5, ATP6V0D1, and ATP6V0B." (PMID 38125829, 2023).
esophageal squamous cell carcinoma (1 paper, 2022). Esophageal squamous cell carcinoma (ESCC) is a type of esophageal carcinoma (EC) that can affect any part of the esophagus, but is usually located in the upper or middle third. "A higher expression level of ATP6V0B has been reported in oesophageal squamous cell carcinoma (ESCC) and metastatic melanoma samples." (PMID 35810383, 2022).
lysosomal disorders (1 paper, 2023). "Here, we found that lysosomal channel proteins (ATP6V0B, ATP6V1E1, ATP6V0D1, ATP6V1F) were significantly decreased in AD, which may mediate the elevation of lysosomal pH leading to lysosomal disorders." (PMID 37334737, 2023).
pancreatic cancer (1 paper, 2025). "We also leveraged LDA, LASSO, and random forest to evaluate ATP6V0B’s potential as a biomarker for early-stage pancreatic cancer diagnosis." (PMID 40598203, 2025). "However, further investigation is still necessary to fully validate ATP6V0B as a pancreatic cancer biomarker for large-scale cohort." (PMID 40598203, 2025). "We discovered that the ATP6V0B gene from patient plasma EVs could be a highly specific marker for diagnosing pancreatic cancer by validating a pilot cohort of 22 plasma samples (6 healthy, 16 patients including 6 matched tumor tissues)." (PMID 40598203, 2025).
pancreatic tumor (1 paper, 2025). "We identified a novel EV biomarker for pancreatic tumor, ATP6V0b, validated with quantitative PCR (qPCR) by screening a pilot cohort of 22 plasma samples." (PMID 40598203, 2025). "The level of ATP6V0B gene is comparable between pancreatic tumor derived EVs and PDAC patient plasma derived EVs." (PMID 40598203, 2025). "We extracted their gene ontology, revealing that ExCy discovered marker, ATP6V0B, is a highly relevant EV marker that increases acidification (logFC = 2.02) of the endosomal and Golgi lumen in pancreatic tumors, dysregulating both EV production and cytosolic ion-channel gradients." (PMID 40598203, 2025). "The discovered ATP6V0B may serve as a novel biomarker for early-detection of PDAC using circulating EVs, and broadly, as a hallmark to understand pancreatic tumor progression." (PMID 40598203, 2025).
schizophrenia (1 paper, 2023). A major psychotic disorder characterized by abnormalities in the perception or expression of reality. "As expected, there was also limited concordance between schizophrenia and ADHD (r = 0.0705), particularly for downregulated genes, and six (MAD1L1, KDM4A, IPO13, ATP6V0B, DPH2, PTPRF) of the nine placental genes associated with ADHD were also significantly associated with schizophrenia." (PMID 37188697, 2023).
tumor (4 papers, 2016 to 2025). "In the TCGA dataset, the expression levels of AKR1B10, ARL6IP4, ATP6V0B, and BSG were significantly up-regulated in the tumor samples." (PMID 38913193, 2024). "Validation analysis confirmed the up-regulation of model genes, including AKR1B10, ARL6IP4, ATP6V0B, and BSG in tumor tissues." (PMID 38913193, 2024). "The model includes seven key genes—SNX5, YBX1, GNPD1, RAB32, TPM3, ATP6V0B, and RAB7A—which may be involved in tumor growth, immune escape, and microenvironment remodeling and may serve as potential targets for therapy." (PMID 41031219, 2025).
infection (1 paper, 2025). The state of being infected such as from the introduction of a foreign agent such as serum, vaccine, antigenic substance or organism. "Fibroblast growth factor (FGF)-23, TFRC, FGFR4, and ATPase H+ transporting V0 subunit B (ATP6V0B) were the upregulated genes identified in A. baumannii without resistant gene infection-associated pulmonary host responses." (PMID 39857726, 2025). "The ATP6V0B gene plays a crucial role in regulating the immune response to Vibrio vulnificus infection in half-smooth tongue sole, with its expression significantly upregulated in key tissues, including the liver, spleen, blood, and heart tissues, during the early stages of infection." (PMID 39857726, 2025).
ATP6V0B also shares sentences with these, for which no sentence is quoted: cancer (2 papers); atherosclerosis (1); metastatic melanoma (1); primary immunodeficiency (1); Salmonella Infections (1).